PARD3 (par-3 family cell polarity regulator)
Description:
Adapter protein involved in asymmetrical cell division and cell polarization processes. Seems to play a central role in the formation of epithelial tight junctions. Targets the phosphatase PTEN to cell junctions (By similarity). Involved in Schwann cell peripheral myelination (By similarity). Association with PARD6B may prevent the interaction of PARD3 with F11R/JAM1, thereby preventing tight junction assembly (By similarity). The PARD6-PARD3 complex links GTP-bound Rho small GTPases to atypical protein kinase C proteins. Required for establishment of neuronal polarity and normal axon formation in cultured hippocampal neurons.
Synonyms: PAR-3; PARD-3; ASIP; PAR3; PARD3A; Bazooka; Baz; PPP1R118; PAR3alpha; SE2-5L16; SE2-5LT1; SE2-5T2
Tractability: Antibody: UniProt places it where antibodies can reach, with high confidence; its Gene Ontology location is reachable by antibodies, with high confidence; the Human Protein Atlas places it where antibodies can reach. PROTAC: ubiquitination databases record sites on it; its protein half-life has been measured.
Gene: Protein-coding gene on chromosome 10 (34,109,560 to 34,815,419, reverse strand). Ensembl gene ENSG00000148498.
Subcellular location: Cytoplasm; Endomembrane system; Cell junction; Cell junction, tight junction; Cell junction, adherens junction; Cell membrane; Cytoplasm, cell cortex; Cytoplasm, cytoskeleton
Subcellular location (Human Protein Atlas): Cell Junctions; Plasma membrane
Pathways (Reactome):
Cell-Cell communication: Tight junction interactions
Signal Transduction: TGF-beta receptor signaling in EMT (epithelial to mesenchymal transition)
Gene Ontology:
Molecular function: protein binding; phosphatidylinositol binding; phosphatidylinositol-3,4,5-trisphosphate binding; phosphatidylinositol-3-phosphate binding; phosphatidylinositol-4,5-bisphosphate binding
Biological process: establishment or maintenance of epithelial cell apical/basal polarity; asymmetric cell division; axonogenesis; bicellular tight junction assembly; cell adhesion; establishment of cell polarity; establishment of epithelial cell polarity; establishment or maintenance of cell polarity; intracellular protein localization; microtubule cytoskeleton organization; myelination in peripheral nervous system; negative regulation of peptidyl-threonine phosphorylation; phospholipase C-activating G protein-coupled receptor signaling pathway; positive regulation of myelination; protein targeting to membrane; protein-containing complex assembly
Cellular component: anchoring junction; bicellular tight junction; cell junction; cell-cell junction; PAR polarity complex; plasma membrane; adherens junction; apical junction complex; apical plasma membrane; cell cortex; cytosol; internode region of axon; tight junction; cytoplasm; cytoskeleton; endomembrane system
Genetic constraint (gnomAD): Loss-of-function variants: 57 observed, 116.51 expected, observed/expected ratio (o/e) 0.49, 90% interval 0.39 to 0.61. The upper end of that interval is the gene's LOEUF score, 0.61, which puts it in group 2 of 6, group 1 being the genes least tolerant of losing a copy. Missense variants: 1,401 observed, 1,490.4 expected, observed/expected ratio (o/e) 0.94, 90% interval 0.9 to 0.98. Synonymous variants: 501 observed, 543.93 expected, observed/expected ratio (o/e) 0.92, 90% interval 0.86 to 0.99.
Homologues: Orthologues: chimpanzee PARD3 (99% identical), macaque PARD3 (99% identical), dog PARD3 (94% identical), pig PARD3 (93% identical), mouse Pard3 (90% identical), guinea pig PARD3 (88% identical), rat Pard3 (87% identical), rabbit PARD3 (81% identical), tropical clawed frog pard3 (81% identical), zebrafish pard3ab (65% identical), zebrafish PARD3 (26% identical), Drosophila melanogaster baz (25% identical), and 1 more. Paralogues in human: PARD3B (36% identical).
Diseases named in the same sentence as PARD3 in open-access papers:
PARD3 is named in the same sentence as 85 diseases in open-access papers, as found by Europe PMC text mining. Sharing a sentence is not in itself a finding about the gene and the disease. The quoted sentences say what the papers report.
hepatocellular carcinoma (5 papers, 2013 to 2024). A malignant tumor that arises from hepatocytes. "Overexpression of PARD3 maintained the self-renewal ability of the CD133+ TIC population within hepatocellular carcinoma (HCC) cells and promoted the in vitro and in vivo tumorigenicity of CD133+ TICs." (PMID 38317186, 2024). "To screen a biomarker closely related to the formation and progression of HCC, we analyzed the differential expression of PARD3 and its clinicopathological relevance, using liver hepatocellular carcinoma (LIHC) RNA sequencing (RNA-seq) data of HCC patients from The Cancer Genome Atlas (TCGA)." (PMID 34040099, 2021).
breast carcinoma (4 papers, 2019 to 2024). "In contrast, in breast cancer, the loss of Pard3 promoted metastasis and decreased cell–cell cohesion, which occurred in the absence of EMT induction." (PMID 30171257, 2019). "For example six SEREX antigens identified in serum from breast cancer patients (RAD50, PARD3, SPP1, SAP30BP, NY-BR-62, and NY-CO-58) could identify breast cancer patients from healthy donors with 70% sensitivity and 91% specificity." (PMID 33976232, 2021).
celiac disease (4 papers, 2013 to 2025). An autoimmune genetic disorder with an unknown pattern of inheritance that primarily affects the digestive tract. "It is worth noting that MYO9B, PARD3, and MAGI2 were also reported to be celiac disease susceptibility genes." (PMID 24062746, 2013). "Previous studies suggest that PARD3 is linked to IBD, celiac disease, CD, and UC." (PMID 40625359, 2025). "There are 39 gene loci showing variation in Celiac Disease patients, at least four of which are known to play roles in cell–cell adhesion (LPP, C1orf106, PTPRK and PARD3), one piece of evidence suggesting a primary barrier defect may exist in Celiac Disease." (PMID 35328419, 2022). "Similar to MYOIXB, PARD3, and MAGI2 variants, the DLG5 R30Q polymorphism has also been reported to be associated with celiac disease, corroborating the concept that a common mechanism, that is breakdown of the intestinal barrier, may exist between celiac disease and IBD." (PMID 24062746, 2013).
gastric cancer (4 papers, 2020 to 2025). A primary or metastatic malignant neoplasm involving the stomach. "These aptamers were used for detecting APOA1, Importin subunit alpha-1, PARD3, and APOA4 gastric cancer biomarkers; where Importin subunit alpha-1 is the strongest candidate to be used for further gastric cancer diagnosis." (PMID 32659966, 2020).
glioblastoma (4 papers, 2021 to 2024). The most malignant astrocytic tumor (WHO grade IV). "Similarly, the same gene can have oncogenic or tumor-suppressive functions in different tissues; for example, PARD3/Par3 overexpression is associated with renal cancers, but PARD3 downregulation or deletion is associated with breast, glioblastoma, lung, and other cancers." (PMID 34137371, 2021). "Although PARD3 expression is differentially regulated in human cancers, and PARD3 may function as either an oncogene or tumour suppressor depending on cancer subtype or stage, a recent study showed that in human glioblastoma, PARD3 was enriched in NESTIN-positive stem cells." (PMID 38317186, 2024).
glioma (4 papers, 2014 to 2024). A benign or malignant brain and spinal cord tumor that arises from glial cells (astrocytes, oligodendrocytes, ependymal cells). "Similar to our findings, silencing PARD3 was found to lead to a defect in glioma sphere formation in vitro, suggesting that the self-renewal capacity of TICs was lost upon PARD3 silencing." (PMID 38317186, 2024). "Firstly, our data shows that direct targeting of proteins such as CD44, CHI3L1 or PARD3 may be ineffective at this stage of disease as they are already downregulated in glioma cells at the AOI." (PMID 25365423, 2014). "We analyzed PARD3 gene expression in GBM versus other glioma types and non-tumor tissues in The Cancer Genome Atlas (TCGA), Gravendeel, and REMBRANDT databases using the GlioVis data portal." (PMID 34642295, 2021).
colorectal cancer (3 papers, 2019 to 2024). A primary or metastatic malignant neoplasm that affects the colon or rectum. "Also, activation of PARD3 signaling was associated with the increased autophagy activity and colorectal cancer cell proliferation." (PMID 36105681, 2022). "PARD3 overexpression enhanced autophagy and promoted the development of colorectal cancer." (PMID 36105681, 2022).
esophageal squamous cell carcinoma (3 papers, 2013 to 2024). Esophageal squamous cell carcinoma (ESCC) is a type of esophageal carcinoma (EC) that can affect any part of the esophagus, but is usually located in the upper or middle third. "Genome-wide screens have revealed that the gene encoding PARD3 is missing in esophageal squamous cell carcinoma, lung cancer, and head and neck cancer cell lines." (PMID 39063214, 2024). "Genome-wide screening for microdeletions revealed that the region containing the Par3 gene (PARD3) is deleted in lung, head and neck, and esophageal squamous cell carcinoma cell lines." (PMID 27855669, 2016). "For instance, Par-3 protein or RNA expression was downregulated in esophageal squamous cell carcinoma and HCC, but PARD3 gene was found mutationally inactivated in prostate cancer cells." (PMID 23322019, 2013). "Par-3 expression and regulation are considered largely involved in cancer cell migration, and a few studies have suggested defective expression or amplified PARD3 gene in prostate cancer cells, esophageal squamous cell carcinoma, neoplastic retinal pigment epithelial cells and HCC." (PMID 23322019, 2013).
cleft palate (2 papers, 2022 to 2024). Cleft palate is a fissure type embryopathy that affects the soft and hard palate to varying degrees. "Regarding rare sequence-level variants, a heterozygous frameshift variant, NM_019619.4(PARD3): c.1012dupG (p.Glu338GlyfsTer26), was identified in six patients from a Chinese family manifesting nonsyndromic isolated cleft palate." (PMID 38300321, 2024). "Based on these data, we reveal PARD3 gene variation as a novel candidate cause of nonsyndromic cleft palate only." (PMID 35789100, 2022). "Furthermore, 6 missense variants in PARD3 found in our cohort of sporadic 57 NSCP cases suggests that missense variants may also contribute to cleft palate risk, although further investigation of the functional impact and role of such missense variants is warranted." (PMID 35789100, 2022).
cyst (2 papers, 2017 to 2026). A sac-like closed membranous structure that may be empty or contain fluid or amorphous material. "The mouse fusome distributes asymmetrically among cyst cells and enriches in future oocytes with Pard3 and Golgi-endosomal UPR (unfolded protein response) proteins." (PMID 41811096, 2026). "Previous work has shown that Par3 (Pard3) is required for cyst formation by establishing PEC polarity." (PMID 28465335, 2017).
Hydrocephalus (2 papers, 2013 to 2014). Hydrocephalus is an active distension of the ventricular system of the brain resulting from inadequate passage of CSF from its point of production within the cerebral ventricles to its point of absorption into the systemic circulation. "PARD3 depletion in zebrafish results in intracellular cilia and hydrocephalus." (PMID 23349908, 2013).
lung squamous cell carcinoma (2 papers, 2021 to 2022). "PARD3 contains multiple postsynaptic densities and is localized to tight junctions; in addition, it is correlated with invasion in lung squamous cell carcinoma via impaired STAT3 signaling." (PMID 36213124, 2022).
Obesity (2 papers, 2015 to 2024). Accumulation of substantial excess body fat. "Obesity mostly upregulated DEGs in endothelial cells for pathways regulating endothelial permeability such as focal adhesion (Prkcb and Vegfc), adherens junction (Pard3), leukocyte transendothelial migration (Prkcb and Vcam1), and Rap1 signaling (Pard3, Prkcb, and Vegfc)." (PMID 39456952, 2024). "However, 4/11 have known or potential roles in obesity, MYO1C, PLIN4, PARD3 and PDE7B." (PMID 25651499, 2015).
ovarian carcinoma (2 papers, 2021 to 2024). A malignant neoplasm originating from the surface ovarian epithelium. "Interestingly, in ovarian cancer, a high expression of PARD3 is associated with poor patient prognosis and may contribute to peritoneal metastasis." (PMID 39063214, 2024). "For instance, PARD3 acts as a tumor suppressor in lung, bladder, breast, cervical, esophageal and pancreatic cancers and malignant melanoma, but it is found to be activated in ovarian cancer and clear-cell renal carcinoma." (PMID 34040099, 2021).
prostate carcinoma (2 papers, 2009 to 2013). A carcinoma that arises from epithelial cells of the prostate gland. "The mutational inactivation in a prostate cancer cell line of the PARD3 gene involved in asymmetric cell division and maintenance of cell-polarity suggests that the loss of cell-polarity contributes to prostate carcinogenesis." (PMID 19737411, 2009). "Using an improved version of GINI, we identified biallelic inactivating mutations in the AS3 and PARD3 genes in prostate cancer cell lines." (PMID 19737411, 2009). "Inactivation in a prostate cancer cell line of the PARD3 gene, involved in asymmetric cell division and maintenance of cell-polarity suggests that the loss of cell-polarity contributes to prostate carcinogenesis." (PMID 19737411, 2009).
schizophrenia (2 papers, 2018 to 2025). A major psychotic disorder characterized by abnormalities in the perception or expression of reality. "One of the new loci that we identified was shared between AN and age at menarche (locus 5) and between AN and BMI (locus 12) and mapped to PARD3, which is involved in various neurodevelopmental, cellular, metabolic and developmental processes and has been linked to schizophrenia." (PMID 39971893, 2025). "In addition, PARD3 and HDAC9 have been both implicated in mental disorders such as schizophrenia." (PMID 29631039, 2018).
thyroid cancer (2 papers, 2019). "Pard3 expression was detected in the four different types of thyroid cancer tissue by immunohistochemistry (IHC)." (PMID 30171257, 2019). "The effects of miR-483 and Pard3 on the TGF-β1-induced progression of thyroid cancer were characterized in the present study." (PMID 30171257, 2019). "In thyroid cancer patients, a decreased disease-free survival was correlated with a reduction in Pard3 expression, when using Kapan–Meier analyses." (PMID 30171257, 2019). "The results showed that after binding of Pard3 and miR-483, the miR-483 downregulated Pard3 in thyroid carcinomas." (PMID 30171257, 2019). "In the current study, we showed that Tiam1/Rac1 signaling was regulated by Pard3 in thyroid carcinomas." (PMID 30171257, 2019). "Our findings showed that miR-483 upregulated Tiam1/Rac1 signaling in thyroid carcinomas, possibly by downregulating Pard3." (PMID 30171257, 2019). "In addition, the miR-483 promotion of TGF-β1-induced thyroid cancer cell proliferation, migration, and invasion, both in vitro and in vivo, was possibly mediated by the downregulation of Pard3." (PMID 30171257, 2019). "The loss of PARD3 occurs in thyroid cancer (as compared to a nontumoral counterpart); and low levels of PARD3 are inversely correlated with miR-483-3p expression." (PMID 31482959, 2019). "The migration and invasion of thyroid cancer cells may be influenced by miR-483, in a mechanism involving regulation of Pard3 expression and Tiam/Rac1 signaling." (PMID 30171257, 2019). "Tumor proliferation promoted by the regulation of miRNA expression can be regulated in thyroid cancer by upregulating transforming growth factor-β1 (TGF-β1), which is thought to interact with Pard3." (PMID 30171257, 2019). "Overall, the results of the present study have shown that Pard3 inhibited TGF-β1-induced cell EMT and invasion, concomitant with miR-483 downregulating Pard3 in thyroid carcinoma cells, to activate Tiam/Rac1 signaling and promoting EMT, as well as cell migration and invasion." (PMID 30171257, 2019).
type 2 diabetes (2 papers, 2015 to 2017). "PARD3 has been identified as candidate gene for its association with type 2 diabetes in Mexican study." (PMID 28558807, 2017).
viral infection (2 papers, 2024). "However, in patients without a history of hepatic viral infection, high expression of PARD3 was associated with unfavorable overall and recurrence-free survival." (PMID 38317186, 2024). "Proteomic analysis comparing PEDV-infected and non-infected groups revealed that PARD3 is a significantly downregulated protein during virus infection." (PMID 38505001, 2024).
acute pancreatitis (1 paper, 2013). An acute inflammatory process that leads to necrosis of the pancreatic parenchyma. "We performed a candidate gene study for MYO9B, PARD3 and MAGI2 looking for susceptibility to acute pancreatitis." (PMID 24386489, 2013). "Five single nucleotide polymorphisms (SNPs) in MYO9B, two SNPs in PARD3, and three SNPs in MAGI2 were studied in a Dutch cohort of 387 patients with acute pancreatitis and over 800 controls, and in a German cohort of 235 patients and 250 controls." (PMID 24386489, 2013). "We investigated genetic variation in MYO9B, PARD3 and MAGI2 for association with acute pancreatitis." (PMID 24386489, 2013). "Both PARD3 SNPs were associated with acute pancreatitis, but these associations did not withstand correction for multiple testing." (PMID 24386489, 2013).
Anxiety (1 paper, 2021). Intense feelings of nervousness, tension, or panic often arise in response to interpersonal stresses. "Other genes previously linked to mood, anxiety, or trauma-related disorders included protein zeta-1 (FEZ1), ADCYAP1, BRSK2, catenin alpha 3 (CTNNA3), and par-3 family cell polarity regulator (PARD3)." (PMID 34799556, 2021).
autism spectrum disorder (1 paper, 2020). A spectrum of developmental disorders that includes autism, and Asperger syndrome. "Regarding the impact on human phenotype, there are five publications describing six variants linking PARD3 to autism spectrum disorder (ASD)." (PMID 32344861, 2020).
cervical cancer (1 paper, 2014). A primary or metastatic malignant neoplasm involving the cervix. "Such deletions include PARD6 (PAR6) in lung cancer, PARD3 (PAR3) in lung, head and neck, esophagus, prostate and bladder cancers, and DLG2 in lung and cervical cancers." (PMID 23771628, 2014).
colon carcinoma (1 paper, 2019). "This notably includes Pard3, which has been found to be periodically recruited to the nuclear envelope in human colon cancer cells, but in mouse liver is localized 15 Mb away from the nearest (and conserved) LAD." (PMID 31632442, 2019).
Crohn disease (1 paper, 2017). A gastrointestinal disorder characterized by chronic inflammation involving all layers of the intestinal wall, noncaseating granulomas affecting the intestinal wall and regional lymph nodes, and transmural fibrosis. "Allelic associations between TJ-related genes (F11R, MAGI1, MAGI2, MAGI3, PARD3, PTEN, and TJP1) and IBD, Crohn’s disease (CD), or ulcerative colitis (UC) were investigated." (PMID 28545409, 2017).
esophageal cancer (1 paper, 2021). A primary or metastatic malignant neoplasm involving the esophagus. "In esophageal cancer, PARD3 overexpression promotes cell apoptosis, inhibits cell proliferation, and inhibits cell migration and invasion, whereas PARD3 silencing promotes cell proliferation and increases migration and invasion." (PMID 34306007, 2021).